DNM2 (dynamin 2)
Diseases named in the same sentence as DNM2 in open-access papers (continued):
Sharing a sentence is not in itself a finding about the gene and the disease.
dementia (1 paper, 2023). Loss of intellectual abilities interfering with an individual's social and occupational functions. "DNM2 pathogenic variants cause a spectrum of neuromuscular diseases but no involvement in dementia or altered Cu metabolism has been documented." (PMID 37047347, 2023).
diabetes (1 paper, 2021). "Dynamin 2, which is involved in vesicle scission during endocytosis, was also more O-GlcNAcylated in placentas from women with both types of diabetes and we identified numerous modification sites withing the protein." (PMID 34667181, 2021).
fibrous dysplasia (1 paper, 2021). A genetic, non-inheritable disorder caused by osteoblastic differentiation defects that result in the replacement of bone marrow and trabecular bone by fibrous stroma and immature bone. "The patient, a boy born in 1991, showed pronounced polyostotic fibrous dysplasia due to McCune–Albright syndrome, as well as Gilbert syndrome and Charcot–Marie–Tooth neuropathy caused by a DNM2 mutation." (PMID 33684277, 2021).
invasive breast carcinoma (1 paper, 2020). A carcinoma that infiltrates the breast parenchyma. "In the present study, the membranous, cytoplasmic, and nuclear expression levels of dynamin 2 molecule were evaluated for the first time, using immunohistochemistry (IHC) on tissue microarray (TMA) slides in 113 invasive breast cancer tissues." (PMID 33250680, 2020).
invasive carcinoma (1 paper, 2024). A carcinoma that is not confined to the epithelium, and has spread to the surrounding stroma. "Importantly, our findings indicated that nuclear expression of DNM2 in the tissues is associated with prominent clinicopathological features, including advanced pT stage, grade, recurrence, and more metastatic and invasive carcinomas." (PMID 39610009, 2024).
leiomyosarcoma (1 paper, 2023). An uncommon, aggressive malignant smooth muscle neoplasm, usually occurring in post-menopausal women. "The second alteration identified in the leiomyosarcoma sample was the c.688+2T>C variant affecting the DNM2 gene, which appears to lead to the loss of the donor splice site at exon 5 on chr19:10777218." (PMID 36673024, 2023).
Lethal congenital contracture syndrome type 5 (1 paper, 2020). "Lethal congenital contracture syndrome type 5 is also a lethal congenital neuromuscular syndrome known to be caused by homozygous mutations in the DNM2 gene, encoding for protein dynamin-2." (PMID 32670090, 2020).
liver disease (1 paper, 2023). "We uncovered a potential therapeutic strategy for MTM1-related liver disease (i.e., DNM2 inhibition) and set the groundwork for future investigation into MTM1 liver function and into factors and triggers that may modulate the cholestatic phenotype." (PMID 37490339, 2023).
male infertility (1 paper, 2013). The inability of the male to effect fertilization of an ovum after a specified period of unprotected intercourse. "To date, no studies reported any specific correlation between male infertility and DNM2 gene duplication/deletion." (PMID 24373333, 2013).
myelofibrosis (1 paper, 2022). A partial or complete replacement of the bone marrow stroma by fibrous tissue. "Dnm2fl/fl Pf4-Cre (Dnm2Plt–/–) mice lacking the endocytic GTPase dynamin 2 (DNM2) in platelets and megakaryocytes (MKs) develop hallmarks of myelofibrosis." (PMID 36110936, 2022).
Obesity (1 paper, 2015). Accumulation of substantial excess body fat. "We also identified six DMRs which mapped to obesity and related metabolic traits in the GWAS catalogue (PROX1, PHACTR1, SLC22A8, SMAD3, LCAT, DNM2)." (PMID 25651499, 2015).
ophthalmoplegia (1 paper, 2023). Weakness or paralysis of at least one of the muscles controlling the movement of the eye. "An autosomal dominant form of CNM arises due to mutations in the dynamin 2 gene (DNM2) leading to generalized hypotonia and ophthalmoplegia." (PMID 36769228, 2023).
pancreatic ductal adenocarcinoma (1 paper, 2021). An infiltrating adenocarcinoma that arises from the epithelial cells of the pancreas. "Finally, DNM2 expression was also shown to be markedly upregulated in tumors and metastases of patients affected by pancreatic ductal adenocarcinoma and this overexpression contributes to lamellipodia extension, cell migration and invasion." (PMID 34294140, 2021).
pneumonia (1 paper, 2022). An acute, acute and chronic, or chronic inflammation focally or diffusely affecting the lung parenchyma, caused by an infection in one or both of the lungs (by bacteria, viruses, fungi, or mycoplasma.). "Results suggested that 5 proteins with greater node degrees [i.e. catenin beta-1 (CTNNB1), integrin beta-1 (ITGB1), catenin alpha-1 (CTNNA1), dynamin-2 (DNM2), Keratin, type I cytoskeletal 19 (KRT19)] might function as crucial players in pneumonia-related bacterial infection in FMD." (PMID 36387401, 2022).
Respiratory insufficiency (1 paper, 2021). "The three patients with de novo variants had an early onset and respiratory insufficiency, as reported in some other patients with de novo DNM2 variants." (PMID 34463354, 2021).
spina bifida aperta (1 paper, 2022). "The expression of coronin 1A and dynamin 2 was exosome-specific and associated with spina bifida aperta embryogenesis." (PMID 35915349, 2022).
Splenomegaly (1 paper, 2022). Abnormal increased size of the spleen. "DNM2 deletion in platelets and MKs led to severe splenomegaly, independently of Mpl expression, indicating that the extramedullary hematopoiesis of Dnm2Plt–/– mice was not related to impaired Mpl-mediated endocytosis in platelets and MKs." (PMID 36110936, 2022).
sterility (1 paper, 2016). "We demonstrate that ablation of DNM2 in early spermatogenesis results in germ cell arrest during prophase I of meiosis, subsequent loss of all post-meiotic germ cells and concomitant sterility." (PMID 27725702, 2016).
systemic lupus erythematosus (1 paper, 2020). An autoimmune multi-organ disease typically associated with vasculopathy and autoantibody production. "In the third trimester, systemic lupus erythematosus and proteasome were enriched in the acute disease while Fc gamma R-mediated phagocytosis (VAV1, MARCKSL1, WASF2, DNM2, HCK, MAP2K1 genes) and adherens junction (ACTG1, WASF2, SMAD4, CSNK2B, EP300 genes) represented the subclinical category." (PMID 32012176, 2020).
Thrombocytopenia (1 paper, 2022). A reduction in the number of circulating thrombocytes. "In the absence of DNM2-dependent endocytosis in the MK/platelet lineage, combined with the severe MK hypoplasia and thrombocytopenia in the Mpl–/– background, increased levels of these cytokines lead to EB maturation blockage." (PMID 36110936, 2022). "Consistent with previous observations, mice lacking DNM2 in platelets and MKs and/or Mpl ubiquitously developed severe thrombocytopenia, with platelet counts constantly below 200 x 103/μl, which was observed at birth and throughout development." (PMID 36110936, 2022).
Ventricular arrhythmia (1 paper, 2014). "Acute myocardial ischaemia induces the reduced expression of myocardial DNM2, which correlates with the incidence of ventricular arrhythmias." (PMID 25092467, 2014).
tumor (97 papers, 2011 to 2026). "On the other hand, plasticity of cell environment, especially through modification of the extracellular matrix, plays an important role in tumor cell invasion and DNM2 was also implicated in this process." (PMID 34294140, 2021). "In this case, injection of DNM2-depleted cells is associated with decrease in tumor cell proliferation and increase in apoptosis." (PMID 34294140, 2021). "Our finding showed that, a higher nuclear expression of dynamin 2 is significantly associated with an increase in tumor stage (P = 0.05), histological grade (P = 0.001), and age of the patients (P = 0.03)." (PMID 33250680, 2020). "In our study, nuclear expression pattern of dynamin 2 indicated that the increased expression of dynamin 2 was associated with tumor stages." (PMID 33250680, 2020). "This is the first report demonstrating the causal relationship between dynamin 2 expression and PpIX excretion in tumor cells." (PMID 31209282, 2019). "Elevated dynamin 2 expression levels are associated with Gleason score, tumor volume, and PCA-specific mortality." (PMID 28402939, 2017). "A statistically significant association was identified between DNM2 expression in the nucleus and higher histological grade (p = 0.026), advanced pT stage (p = 0.016), muscular invasion (p = 0.007), tumor recurrence (p = 0.030), and distant metastasis (p < 0.001)." (PMID 39610009, 2024). "Aside from its physiological functions, recently published in vitro studies have shown that DNM2 is implicated in numerous tumorigenesis and tumor progression processes, including cancer cell proliferation, chemoresistance, cell migration, motility, invasion, and metastasis." (PMID 39610009, 2024). "Our present findings suggest that DNM2 is involved in primary tumor progression and prognosis in OSCC." (PMID 40419438, 2025). "The relationship between DNM2 expression and clinicopathological factors showed significant differences between DNM2 expression of tumor cells and the T classification and stage, DOI of OSCC." (PMID 40419438, 2025). "The results of univariate Cox regression analysis displayed that nuclear expression of DNM2 (p = 0.034), pT stage (p < 0.001), tumor differentiation (p = 0.002), and muscularis invasion (p < 0.001) were significant risk factors influencing DSS." (PMID 39610009, 2024). "ASAP2, DNM2 and KIF13B encoding signal transduction proteins play crucial roles in tumor proliferation and invasion." (PMID 38529307, 2024). "In a previous study we had observed that blocking EV uptake by the dynamin-2 inhibitor dynasore can inhibit the pro-invasive function of tumor EVs on MCF-7 invasiveness by around 40%." (PMID 37430307, 2023). "The available data strongly suggest that DNM2 participates to the maintenance of the necessarily favourable environment for tumor to grow, invade and migrate." (PMID 34294140, 2021). "The function of the DNM2 in cytokinesis was targeted in order to influence the cell cycle progression and reduce proliferation of tumor cells." (PMID 34294140, 2021). "Intriguingly, an increased expression of DNM2 was also noticed in the nucleus which is positively correlated with the histological grade and the tumor stage." (PMID 34294140, 2021). "Benefit of DNM2 inhibition was largely documented for almost all the DNM2-related phenotypes in tumor cells in vitro." (PMID 34294140, 2021). "DNM2 activity is required for extracellular matrix degradation by invasive tumor cells at invadopodia, another specialized actin-based plasma membrane protrusion." (PMID 34294140, 2021). "Overall, the challenge of future DNM2-based therapies will be to simultaneously maintain DNM2 positive roles and counteract its deleterious functions in tumor cells." (PMID 34294140, 2021). "Second, DNM2 acts on intracellular signaling pathways fostering tumor cell proliferation and survival." (PMID 34294140, 2021).
tumor (continued). "We found a significant difference in cytoplasmic dynamin 2 expression and tumor types in case of the staining intensity (P = 0.003)." (PMID 33250680, 2020). "In this regard, it should be noted that, the pattern of dynamin 2 expression in tumor cells was classified into nuclear, membranous, and cytoplasmic expressions and the analysis was also performed." (PMID 33250680, 2020). "Pearson's χ2 test showed a statistically significant association between the increased expression level of nuclear dynamin 2 with the histological grade (H-score P = 0.001) and tumor stage in case of the staining intensity (P = 0.05)." (PMID 33250680, 2020). "In preclinical models, dynamin 2 gene silencing significantly reduced cell migration and invasion in vitro, as well as tumor size and lymph node metastases in vivo." (PMID 28402939, 2017). "In these studies, cell-permeable iron was able to counteract the effect of Dynamin-2 inhibition on HIF-1α in tumor cells." (PMID 27589831, 2016). "DNM2 acts on intracellular signaling pathways to promote tumor cell survival and proliferation." (PMID 40419438, 2025). "In addition, nuclear expression of DNM2 was directly correlated with grade (p = 0.026), advanced tumor stage (p = 0.021), and muscular invasion (p = 0.007) based on Spearman's correlation test." (PMID 39610009, 2024). "In addition, the results of IHC analysis for DNM2 exhibited membranous and cytoplasmic expression patterns in normal tissue samples adjacent to tumor." (PMID 39610009, 2024). "DNM2 has participated in important signaling pathways with a high confidence score, which dysregulation and activations of these pathways play pivotal functions in carcinogenesis and tumor development." (PMID 39610009, 2024). "It is speculated that, in the tumor microenvironment, under the influence of different stimuli, phosphorylated PKCα synergizes with DNM2 bound to the cytoskeletal proteins to induce cytoskeletal remodeling, extracellular budding, and PEV formation." (PMID 39113702, 2024). "Knockdown of DNM2 impairs DNA repair mechanisms of tumor cells in mice." (PMID 36936429, 2023). "Low intracellular PPIX concentrations after ≤2.5 mM 5-ALA supplementation with FTC might be explained by another type of cellular transport mechanism, such as dynamin 2-mediated exocytosis in tumor cells." (PMID 35215109, 2022). "DNM2 inhibition can also reduce the invasive phenotype of tumor cells in vitro." (PMID 34294140, 2021). "In summary, DNM2 directly impacts tumor cells invasiveness and consequent metastasis by stabilizing distinct actin-based structures involved in cell migration, by remodelling extracellular matrix through metalloproteinase delivery and by promoting focal adhesions disassembly." (PMID 34294140, 2021). "Therefore, evaluation of the dynamin 2 expression patterns at three levels of nuclear, membranous, and cytoplasm is useful to predict the tumor invasiveness and progression of disease." (PMID 33250680, 2020). "Dynamin 2 also regulates polyamine internalization in a colon-derived tumor cell line, HCT116." (PMID 28402939, 2017). "Similarly, the downregulation of RAB5C, RAB7A, and DNM2, involved in endocytosis and vesicular trafficking, suggests interference with receptor signaling, nutrient uptake, and protein degradation, essential for tumor growth." (PMID 40429900, 2025). "It is tempting to speculate that STAT3 activation is involved in DNM2 upregulation in cancers and that DNM2 overexpression may be an effector of features associated with abnormal STAT3 activation in cancers such as tumor growth and metastasis leading to poor prognosis." (PMID 34294140, 2021).
tumor (continued). "Therapeutic potential of DNM2-based approaches may be of particular interest to counteract metastasis which mark the transition from a benign tumor to a lethal, malignant cancer with dissemination of tumor cells." (PMID 34294140, 2021). "Dynamin 2 (DNM2) is aberrantly expressed in different malignancies and exerts a function in tumor progression." (PMID 39610009, 2024). "The expression levels of dynamin 2 molecule were assessed using IHC on TMA sections by three scoring methods as follows: intensity of staining, percentage of positive tumor cells, and H-score." (PMID 33250680, 2020). "After dynamin 2 is knocked down or inhibited, the internalization of EGFR is delayed and reduced, resulting in increased EGF-mediated tumor cell migration, colony formation and invasion." (PMID 28402939, 2017). "Immunohistochemical staining for DNM2 and CAV1 was performed on resected primary tumor specimens from 80 OSCC patients, and the individual expressions and combined expression status of these proteins were analyzed in relation to clinicopathological factors and prognosis." (PMID 40419438, 2025). "With cancer progression, DNM2 expression decreases through an unidentified mechanism leading to low or no expression in high-grade lesions (CIN grades 2 and 3) especially, in case of deep tumor invasion and lymph node metastasis." (PMID 34294140, 2021). "Indeed, when re-expressed or overexpressed in metastatic tumor cells, NME proteins suppress cell motility and migration in vitro and metastatic colonization in vivo through a mechanism requiring DNM2-dependent endocytosis." (PMID 34294140, 2021). "KEAP1, DNM2, SMARCA4 were annotated as tumor suppressor genes in the Cancer Gene Census database." (PMID 32337068, 2020). "In tumor cells, FAC was able to counteract the effect of Dynamin-2 inhibition on HIF-1α." (PMID 27589831, 2016). "Our results reveal that endocytosis plays an unexpected role in gefitinib action and that expression level of endocytosis proteins such as DNM2, LRP-1 or Rab5 could be relevant biomarkers to predict TKI efficiency in limiting dissemination of GBM cells from tumour spheroids." (PMID 34831480, 2021). "In our experimental setup, DNM2 inhibition or repression had no impact in evasion of controlled cells indicating that DNM2 may not play an important function in the capacity of GBM cells to detach from tumour spheroids and to migrate." (PMID 34831480, 2021). "Interestingly, there are genes (e.g., DNM2) whose control increased with respect to NOR in one cancer nodule (PTA, ΔREC(PTA→NOR) = 6.2) but decreased in the equally ranked other nodule from the same tumor (ΔREC(PTB→NOR) = −7.2), indicating a shift in the cell’s priorities." (PMID 38132440, 2023).